AHR (aryl hydrocarbon receptor)
Diseases named in the same sentence as AHR in open-access papers (continued):
Sharing a sentence is not in itself a finding about the gene and the disease.
colitis (continued). "Since the loss of PARP7 expression increases AHR and IFN-I signaling, we used a murine dextran sulfate sodium (DSS)-induced colitis model to investigate the effect of PARP7 loss on DSS-induced intestinal inflammation." (PMID 35055106, 2022). "Another study suggested that AHR reduces inflammation in experimental colitis via the downregulation of the MK2/p-MK2/TTP pathway." (PMID 35923391, 2022). "In this study, we discovered enhanced ISC regeneration and increased intestinal IL-22 secretion and its related transcription factor AHR in colitis mice after L-fucose treatment." (PMID 36432480, 2022). "It does not exceed our expectation because Lactobacillus has been reported to possess the ability to convert tryptophan to indole alkaloids and active aryl hydrocarbon receptor (AhR) to alleviate murine colitis." (PMID 34354708, 2021). "Further, haplodeficiency of RORγt with genetic ablation of AhR spontaneously induces colitis indicating the importance of RORγt in maintaining the ILC3 compartment and subsequent IL-22 production in tandem with AhR activation." (PMID 33777031, 2021). "Indole alkaloids have been proved as essential protective agents in colitis by activating AhR and inducing subsequent IL-22-depedent regeneration of mucosal barrier integrity." (PMID 34354708, 2021). "In fact, supplementation with dietary tryptophan and indole metabolites protects against colitis through AhR." (PMID 34062869, 2021). "Our laboratory has previously shown that TCDD-induced AhR activation employed DNA methylation mechanisms to reverse the demethylation of IL-17 promoters in colitis, thus inhibiting Th17 cells and attenuating inflammation." (PMID 35008717, 2021). "In mice models, consumption of broccoli increased intestinal AHR activity, reduced microbial abundance of Erysipelotrichaceae and impaired colitis." (PMID 33806061, 2021). "Alpinetin (a flavone) also isolated from Alpinia katsumadai Hayata seeds alleviated colitis through restoring Th17/Treg balance in the colon via activation of AhR." (PMID 34249001, 2021). "IA was reported to promote barrier function and immune tolerance in DSS-induced colitis mice, which is related to inducing the mRNA expression of the AhR target gene Cyp1a1 in the intestinal epithelium and immune cells by IA." (PMID 34966278, 2021). "Further evidence indicated that AhR is an inhibitor of NLRP3 inflammasome in bowel inflammation and colitis-associated colorectal cancer." (PMID 34868022, 2021). "AHR is known to have a role in modulating intestinal inflammatory responses, thereby exerting protective effects against colitis." (PMID 34502047, 2021). "Microbial indole-derivatives, including IAld, have been shown to ameliorate EAE and colitis in an AhR-dependent manner." (PMID 33670600, 2021). "Multiple studies have demonstrated that Trp feeding ameliorates DSS colitis in an AHR dependent manner, and at least some of that protection can be recapitulated by feeding with microbial metabolites." (PMID 34149693, 2021). "In a T cell–mediated colitis mice model, oral administration of IPyA, a microbiota-derived AHR agonist, decreases the frequency of IFN-γ+ IL-10- CD4+ T cells and increases that of IFN-γ- IL-10+ CD4+ T cells in the colon lamina propria." (PMID 34966278, 2021). "In another study, AhR activation by TCDD was shown to enhance the induction of miR-132 expression and attenuate colitis-associated colon cancer by suppressing the infiltration of macrophages and the production of inflammatory cytokines." (PMID 33679792, 2021). "Nevertheless, this approach was sufficient to show that natural, plant-derived AhR ligands can restore clinical symptoms and histopathology in the moderate (Q or I3C) or even in the severe colitis model (I3C) in an AhR-dependent manner." (PMID 33668818, 2021). "IBD symptoms and pro-inflammatory cytokine levels were found to be greater in AHR knockouts in murine models of dextran sodium sulfate (DSS)-induced colitis." (PMID 34073220, 2021).
colitis (continued). "In preclinical models of colitis and IBD patients, changes of AhR expression are associated with alterations of the serum and fecal levels of several AhR ligands." (PMID 33562721, 2021). "This is a valid explanation for the protection from colitis through I3C, although it appears to be at least partially AhR-independent." (PMID 32366032, 2020). "Oral administration of heat-killed L. Bulgaricus shows improvement in DSS-colitis mice by activating the AhR pathway and inducing mRNA expression of CYP1A1, one of the AhR pathway target genes." (PMID 32957545, 2020). "Together, these findings in rodent models suggest that disruption of the Trp metabolites/AhR signaling axis is a key mechanism in colitis development." (PMID 32957545, 2020). "Studies in experimental colitis mouse models have shown an attenuation of inflammation after administration of a potent AhR agonist (FICZ), derived from UV light oxidation." (PMID 32957545, 2020). "Metabolites of indole pyruvic acids including IAA, indoxyl, and IAcrGly are ligands to aryl hydrocarbon receptor (AHR), a transcriptional regulator for intestinal innate immunity and inflammation in the colitis-associated tumorigenesis." (PMID 33123283, 2020). "Another study suggested that AhR reduces inflammation in experimental colitis via the MK2/p-MK2/TTP pathway." (PMID 32957545, 2020). "A similar phenomenon was observed in DSS-induced colitis mice, while activation of AhR effectively alleviated colitis mice." (PMID 33082710, 2020). "In this model, miRNA analysis showed that while colitis increased the expression of the miR-212/132 cluster, in AhR (−/−) mice, this expression was decreased." (PMID 33105907, 2020). "A tryptophan-free diet exacerbates pathology in colitis models, whereas Lactobacillus bulgaricus, an AhR-activating bacterium, ameliorates pathology." (PMID 33424846, 2020). "Conversely, knockout of AhR specifically in intestinal epithelial cells has deleterious consequences on the outcome of experimental colitis." (PMID 32017483, 2020). "Studies from our lab showed that TCDD-induced activation of AhR promoted the generation of Tregs that suppressed experimental colitis in mice." (PMID 33105907, 2020). "The role of I3C and cruciferous vegetables in modulating pathogen-induced intestinal inflammation, via AhR-dependent signaling, has been reported for the Citrobacter rodentium (Cr) -induced colitis model." (PMID 32230738, 2020). "This study suggested that I3C activation of AhR attenuates colitis primarily through the induction of IL-22, which leads to dysbiosis that promotes the production of anti-inflammatory butyrate." (PMID 33105907, 2020). "Deletion of AhR in T cells was shown to attenuate colitis, which results from suppressed Th17 cell infiltration into the lamina propria." (PMID 33105907, 2020). "To examine the relevance of these pathways in colitis, we tested the in vivo requirement for Nrf2 and AhR." (PMID 30626868, 2019). "In conclusion, data of the present work confirm and expand on previous results of studies showing the benefit of AhR activation on the course of experimental colitis, supporting the notion that AhR can be a valid target for therapeutic interventions in IBD." (PMID 31031628, 2019). "Further studies are warranted using Villin Cre AhR floxed mice, to tease out involvement of AhR in UroA/UAS03 mediated protective activities in colitis models." (PMID 30626868, 2019). "Production of proinflammatory cytokines in intestinal epithelial cells can be attenuated by upregulation of AhR activity; and enhanced AhR activation alleviates inflammatory diseases, including colitis, in experimental animals." (PMID 31684930, 2019). "In this model, treating TNBS mice with Mt-P dose-dependently rescued from development of colitis in an AhR-dependent manner." (PMID 31394746, 2019).
colitis (continued). "AhR activation in IECs protects mice from colitis by enhancing IECs barrier functions via the increase of the IL10 receptor expression and the enhancement of tight junctions integrity through the regulation of Notch119,20." (PMID 30679727, 2019). "After the induction of TNBS colitis, Ficz and AhR ligands were injected intra-peritoneally to wild type and AhR knock-out mice." (PMID 31031628, 2019). "The gastrointestinal tract is a rich source of AhR ligands, which have been shown to induce AhR dependent responses and to protect the gut upon infection or induced colitis." (PMID 30679727, 2019). "AhR antagonism leads to more severe chemically-induced colitis, and expression of AhR is reduced in intestinal tissue of ulcerative colitis (UC) patients." (PMID 31604984, 2019). "In conclusion, alpinetin ameliorated colitis in mice via activating AhR, regulating miR-302/DNMT-1/CREB signals, therefore promoting Treg differentiation." (PMID 30166541, 2018). "Several reports have demonstrated that administration of AhR agonists markedly attenuated experimentally induced colitis in mice." (PMID 29666456, 2018). "In a murine TNBS colitis model, an AhR antagonist induced more severe colitis by suppressing synthesis of IL-22." (PMID 29910812, 2018). "In conclusion, NOR promoted Treg differentiation and then alleviated the development of colitis by regulating AhR/glycolysis axis and subsequent NAD+/SIRT1/SUV39H1/H3K9me3 signaling pathway." (PMID 29449535, 2018). "During acute colitis, Trp supplementation protects the epithelial layer and prevents the intestinal inflammation mediated by AhR signaling." (PMID 29468141, 2018). "In a DSS-inducible intestinal injury murine model, dietary Trp alleviated colitis symptoms and severity through the activation of AhR." (PMID 29468141, 2018). "In DSS-induced colitis mice, dysbiosis alters tryptophan metabolites production, and in turn, lessens the activation of AHR, affecting the host’s immune response and disrupting intestinal homeostasis." (PMID 28726741, 2017). "In AhR−/− mice, the frequency of Th17, Th1, as well as Tc1 cells but not Tc17 cells was enhanced, in line with previous findings in a different colitis model." (PMID 27184933, 2016). "Our finding that genetic deficiency of either AhR or AhRR exacerbates intestinal inflammation in the DSS colitis model at first glance questions the inhibitory action of the AhRR on AhR activity." (PMID 27184933, 2016). "A recent study showed a different molecular mechanism of the AhR signaling pathway in the process of improving the DSS-induced colitis in mouse model." (PMID 24905409, 2014). "One study showed that dextran sodium sulfate (DSS)-induced colitis was ameliorated by pretreatment with the potent AhR agonist, TCDD, in mice." (PMID 24905409, 2014). "At the same time the author also found that DSS-evoked colitis was more severe in AhR knockout mice than in C57BL/6J wild type mice." (PMID 24905409, 2014). "AhR−/− mice are more sensitive to DSS colitis than WT mice while AhR−/+ mice are less sensitive and exhibit a decreased expression of TNF and IL-17 and an increased expression of IL-10 as we observed in our model." (PMID 23638007, 2013). "A previous study demonstrated that TCDD-induced AhR activation ameliorates inflammation in the mouse colitis model." (PMID 23533402, 2013). "We observed demethylation of CpG islands present in the Foxp3 promoter and increased methylation of CpG islands of the IL-17 promoter, following activation of AhR during colitis." (PMID 21858153, 2011). "Because of the low recovery of cells from LP, and the low frequency of Tregs and Th17 cells in the LP and MLN, we performed RT-PCR to further characterize the effect of AhR activation during colitis on induction of Tregs and IL-17." (PMID 21858153, 2011).
colitis (continued). "Given AHR’s broad distribution in barrier organs, our findings provide mechanistic insight into how IMP may modulate autoimmune diseases, like psoriasis and colitis, through tissue-specific AHR activation pathways." (PMID 41513604, 2026). "Similarly, administration of FICZ, an AhR agonist, promoted IL‐22 secretion and significantly ameliorated chemically induced colitis, while AhR antagonists worsened disease severity." (PMID 41583118, 2026). "Mechanistically, inhibitor CH223191 markedly down-regulated the mRNA and protein levels of AhR and its downstream targets CYP1A1 and IL22 in colonic tissue compared with HQD treatment alone, underscoring the critical role of AhR activation in HQD-mediated alleviation of experimental colitis." (PMID 41530817, 2026). "Restoring microbial AhR-ligand biosynthesis ameliorates DSS colitis, presumably because indole derivatives stimulate AhR in immune cells predominantly Group 3 Innate Lymphoid Cells (ILC3) to release IL-22 or activate AhR in IEC, thereby directing differentiation and function of ISC." (PMID 41530817, 2026). "ELNs from mulberry bark impeded DSS‐triggered colitis by regulating AhR/COPS8 signaling." (PMID 41583118, 2026). "To determine whether AhR signalling is indispensable for the therapeutic effects of HQD in DSS-colitis, we pharmacologically blocked the pathway by intraperitoneal administration of the selective antagonist CH223191." (PMID 41530817, 2026). "Pharmacologic AhR inhibition nullified the beneficial actions of HQD against DSS-provoked colitis." (PMID 41530817, 2026). "Microbiota from colitis mice significantly downregulated the mRNA and protein expression of AhR and BD1 compared to cells cocultured with microbiota population from control mice." (PMID 40410944, 2025). "Our results provide the first evidence that AhR activation transcriptionally induces the α-defensin 1 expression through binding to its DREs, leading to reversal of microbial dysbiosis and suppression of colitis." (PMID 39894796, 2025). "In the current study, we investigated the role of AhR expressed by the CECs in the regulation of antimicrobial peptide, BD‐1, and consequent effect on microbial flora in the gut as well as colonic inflammation during colitis." (PMID 40410944, 2025). "AhR activation by I3C treatment enhanced the many members of the Firmicutes as well as Verrucomicroiota phylum and decreased the members of Bacteroidia phylum in colitis mice." (PMID 39894796, 2025). "Furthermore, administration of myricet in significantly increased the relative expressions of CYP1A1 and CYP1B1, whereas AhR inhibitor abolished the amelioration of myricetin on DSS-induced colitis." (PMID 39974840, 2025). "However, I3C treatment enhanced AhR activation followed by α-defensin 1 induction in wild-type colitis mice." (PMID 39894796, 2025). "Additionally, AHR activation facilitates the differentiation of regulatory DC and Tregs, thus limiting experimental colitis in mice." (PMID 41194916, 2025). "The AhR agonist β-naphthoflavone significantly reduces colitis induced by DSS." (PMID 41031160, 2025). "Interestingly, we found a positive correlation between AhR and alpha-defensin 1 protein levels in ileal tissues from active Crohn’s’ (CD) patients and epithelial cells (IECs) from multiple models of murine colitis." (PMID 39894796, 2025). "To investigate if the prevention of dysbiosis by I3C during colitis results in microbiota that promotes AhR or BD‐1 expression, we collected the colonic content microbiota from control, anti‐CD40‐induced colitis, and anti‐CD40+I3C treated mice, and cocultured with MC38 and Caco2 cells for 24 h." (PMID 40410944, 2025). "Collectively, these data suggested that AhR activation by I3C may attenuate colitis by preventing microbial dysbiosis in colitis mice." (PMID 40410944, 2025).
colitis (continued). "In summary, our studies demonstrate that AhR is an essential host factor that transcriptionally induces α-defensin 1 in IECs to regulate gut microorganisms, thereby reversing microbial dysbiosis and attenuating colitis." (PMID 39894796, 2025). "Regulate the intestinal microbiota and activate the AhR—COPS8 pathway to improve colitis." (PMID 40282242, 2025). "Interestingly, microbiota from colitis+I3C treated mice significantly increased the expression of AhR and BD1." (PMID 40410944, 2025). "Moreover, administration of the tryptophan metabolite indole-3-carboxaldehyde has been shown to mitigate DSS-induced colitis in mice through an AHR–IL-22 signaling pathway in the gut." (PMID 40264971, 2025). "This suggests that quercetin’s protective effects against colitis may depend, at least partially, on its ability to activate the AhR pathway." (PMID 41247018, 2025). "In addition, CH223191 was used to further elucidate the role of AhR in the remission of colitis by myricetin." (PMID 39974840, 2025). "The results suggested that myricetin could exert its protection against dextran sulfate sodium (DSS)-induced colitis by activating AhR signaling pathway." (PMID 39974840, 2025). "Notably, AhR antagonists eliminated the beneficial effects of XANA on colitis, but only attenuated the effects of TLB." (PMID 39836604, 2025). "Additionally, research has revealed that β-Glucan ameliorates colitis via the L. johnsonii-indole-3-lactic acid (ILA)-aryl hydrocarbon receptor (AhR) axis." (PMID 40822402, 2025). "This study investigates whether Lactobacillus murinus (L. murinus) attenuates tumor necrosis factor alpha (TNF-α)-induced pro-inflammatory responses in a human intestinal epithelial cell model of colitis by modulating the aryl hydrocarbon receptor (AHR)." (PMID 41373818, 2025). "However, α-defensin 1 which was induced by AhR activation by I3C maintained crypt development and normal colonic tissue architecture and attenuated colitis." (PMID 39894796, 2025). "It was found that AhR could ameliorate inflammation induced by colitis by regulating the balance of Tregs and Th17 cells." (PMID 39974840, 2025). "It is possible that the degree of severity in colitis may depend on whether AhR is deleted only in IECs versus all cells." (PMID 40410944, 2025). "Supplementation with Trp or several microbial Trp metabolites has been demonstrated to protect against colitis in mice through the activation of AhR, followed by the regulation of intestinal barrier, immune response, gut microbiota homeostasis, and other factors." (PMID 41488633, 2025). "Furthermore, activated AhR enhances the expression of IL-22, which helps suppress intestinal inflammation in mice with colitis." (PMID 41031160, 2025). "Similarly, in a DSS-induced colitis model, quercetin restored tight junctions (TJs) in an aryl hydrocarbon receptor (AhR)-dependent manner." (PMID 40225345, 2025). "We next investigated whether AhR‐mediated induction of mBD‐1 plays a role in the regulation of colitis." (PMID 40410944, 2025). "Interestingly, AhR‐mediated transcriptional upregulation of BD‐1 in CECs suppresses microbiota‐driven inflammation and colitis." (PMID 40410944, 2025). "Moreover, AhR-deficient mice develop more severe colitis following DSS treatment than wild-type mice, and AhR ligands have been shown to relieve this colitis, possibly due to sustained T-IEL numbers." (PMID 40005486, 2025). "ILA can ameliorate colitis in caesarean‐born offspring by activating the AhR." (PMID 39854052, 2025). "Notably, the AhR antagonist abrogated the beneficial effects of 5HIAA on colitis but merely attenuated the effects of SH." (PMID 38882491, 2024). "IN and indigo ameliorated experimental colitis by activating the AhR signaling." (PMID 39475104, 2024). "Therefore, we conducted scRNA-seq to analyze intestinal LP CD45+ leukocytes from the colonic tissue of AhR+/+ and AhR-/- mice with colitis." (PMID 39113799, 2024).